KLF4 (KLF transcription factor 4)
Diseases named in the same sentence as KLF4 in open-access papers (continued):
Sharing a sentence is not in itself a finding about the gene and the disease.
tumor (continued). "Therefore, in both GES‐1 and AGS cells, the induced expression of CagA resulted in significantly reduced KLF4 expression of tumor suppressor genes." (PMID 32017451, 2020). "The effect of KLF4 on tumor growth was further investigated in competition assays in vivo when identical numbers of mock-transduced control cells and wtKLF4-transduced cells derived from the same PDX model were mixed and injected into the same animal (indicated in orange)." (PMID 32944247, 2020). "Finally, we observed SMO, LRP, CSKNK2A2, DVL, TEAD, NOTCH1 and KLF4 mutated genes, which are crucial in the regulation of Wnt, Notch and Hedgehog signalling pathways and thus could be the possible culprit behind the enrichment of CSCs in tumour and distal margin." (PMID 30950180, 2019). "For KLF4, both a tumor-promoting as well as a tumor-suppressive role have been described." (PMID 30813586, 2019). "High expression of KLF4 was significantly correlated with increased tumour grade." (PMID 30658712, 2019). "In addition, a significantly higher expression of CSC-related genes (NANOG, OCT4, SOX2, KLF4) was found in spheroids formed from ascites-derived tumor cells, compared to monolayer cells by qPCR." (PMID 31212816, 2019). "The expression level of KLF4 has an inverse relationship with the size of the tumor." (PMID 31724937, 2019). "Importantly, evidence indicates that KLF4 functions as a tumor suppressor that inhibits progression of CRC." (PMID 32566755, 2019). "Both tumor suppressive and oncogenic function of KLF4 has been reported." (PMID 31245293, 2019). "To further investigate whether DDX17 affected the expression of Klf4 target genes responsible for tumor metastasis, we checked the expression of E-cadherin and MMP2, whose promoter or enhancer element is regulated by Klf417,20." (PMID 31653828, 2019). "The correlation is even stronger in patients with advanced disease; the high levels of KLF4 expression could significantly enhance multi-drug resistance, in vitro migration/invasion potential, and in vivo tumor formation." (PMID 31427673, 2019). "Recently, KLF4 has been characterized as a potent tumor suppressor in HCC29." (PMID 30952833, 2019). "KLF4 plays an important role in tumor initiating, growth, and metastasis." (PMID 31969824, 2019). "For the other targets, the reasons for these contradictory results remain speculative and may encompass cellular compensation reactions towards napabucasin treatment or, like KLF4, tumor-specific multi-functionalities." (PMID 30813586, 2019). "Thus, the ability of KLF4 to act as either a tumour suppressor or an oncogene is largely dependent on tissue type, tumour type and tumour stage." (PMID 30176890, 2018). "Induction of pro-inflammatory pathways in tumor myeloid cells by Klf4 deletion might induce immune cell influx and activation." (PMID 29324844, 2018). "We found that KLF4 markedly upregulated both in samples from TCGA and fresh clinical tumor tissues." (PMID 30108202, 2018). "Since OIP5-AS1 is expressed at high level in undifferentiated tumor cells, we asked the question whether the promoter of OIP5-AS1 gene has possible binding motifs for stemness associated TFs (Yamanaka factors) MYC, KLF4, OCT4, SOX2, and NANOG." (PMID 29728583, 2018). "Most of the studies suggested that KLF4 acts as a tumor suppressor." (PMID 30108202, 2018). "One family member, KLF4, can function both as a tumor suppressor and as an oncogene." (PMID 29899271, 2018). "Klf4 and c-Myc are oncogenes, which can initiate tumor growth in vivo." (PMID 29212797, 2018). "In tumours, KLF4 acts as an oncogene or a tumour suppressor depending on the types of cancers." (PMID 30055641, 2018). "Furthermore, inhibition of KLF4 in human OSA xenografts reduced tumor growth in vivo, providing further support for its role in OSA biology." (PMID 29293555, 2018).
tumor (continued). "Interestingly, MDSC-derived fibrocytes are promoted by transcription factor Krüppel-like factor 4 (KLF4) during tumor metastasis, boosting tumor growth as they adopt the cell fate." (PMID 30081463, 2018). "Based on this evidence we hypothesised that the KLF4 activity may derive from immune cells penetrating the tumour." (PMID 30287917, 2018). "In addition, we observed a nearly 2-fold increase in the frequency of tumor CD3+ T cells and a 4-fold increase in tumor CD8+ T cells in response to myeloid Klf4 deletion." (PMID 29324844, 2018). "Plotting the estimated tumor volumes subsequent to day 22 on a logarithmic scale allows fitting later growth rates to best fit lines, with the slopes of these lines on average ~2-fold lower in the Klf4(f/f);Lys-Cre cohort." (PMID 29324844, 2018). "We identified three tumor suppressor genes associated with Wnt pathway, namely, DKK3, KLF4 and GSK3β, that might be the potential targets of miR-92a." (PMID 29254202, 2017). "Further studies showed that overexpression of HOTAIR could promote tumor sphere formation, which upregulated expression of the tumor stem cell-related biomarkers such as Nanog, Oct3/4, Sox2, c-Myc, β-catenin, and Klf4." (PMID 28978188, 2017). "The tumor volume, tumor size and tumor weight were significantly larger in tumors induced by vector-expressing cells compared with tumors induced by Klf4-expressing cells." (PMID 29212199, 2017). "KLF4 has been considered to be a tumor suppressor in HCC by previous studies." (PMID 28978114, 2017). "Tumor xenografts and a lung metastasis model were established to evaluate tumorigenesis in vivo following in vitro studies confirming the tumor suppressor role of KLF4 in UBC." (PMID 29254226, 2017). "Conversely, depletion of endogeneous Klf4 markedly accelerated tumor growth in vivo." (PMID 29212199, 2017). "Among those factors, KLF4 is of full interest to researchers for its role as a tumor suppressor." (PMID 29062163, 2017). "Importantly, KLF4 overexpression mediated by CRISPR-ON system inhibited the growth of tumor xenografts and lung metastasis in vitro." (PMID 29254226, 2017). "In our sample set, we did not observe any atypical tumours that harboured mutations in TRAF7/KLF4, POLR2A or the Hedgehog pathway." (PMID 28195122, 2017). "In addition, the expression levels of KLF4, as assessed by immunohistochemical staining, were increased in tumor regions compared to normal tissue, as shown in Western blot analysis." (PMID 28380435, 2017). "In the present study, we investigate whether Klf4 is involved in stemness, epithelial-mesenchymal transition (EMT) and tumor progression of NPC, as well as the underlying mechanisms." (PMID 29212199, 2017). "KLF4 could inhibit tumor cell proliferation through inducing expression of p21 and/or p27 and downregulation of cyclinD1." (PMID 29062163, 2017). "In the cancer context, KLF4 has mostly been described as a tumor suppressor." (PMID 28412746, 2017). "KLF4 has been confirmed as both anti-oncogene and tumor promoter in different types of cancer." (PMID 28445396, 2017). "Overall, these results supported a tumor suppressor role for KLF4 in UBC." (PMID 29254226, 2017). "The potential effects of KLF4 in tumor carcinogenesis were variable in different malignancies." (PMID 29254226, 2017). "In addition to driving tumor malignancy, KLF4 can act as a tumor suppressor in distinct cellular contexts." (PMID 28553926, 2017). "Besides, statistical analysis revealed the significantly low expression of KLF4 in UBC tissue compared with non-tumor tissue (P < 0.001)." (PMID 29254226, 2017). "The potential downstream targets of KLF4 (e.g., Wnt5A, CCND2) may give us a new thought in the mechanism of KLF4-induced stem-like property that contributes to the tumor-initiating ability." (PMID 26823670, 2016). "All these results demonstrated that miR-135a-5p could promote tumor proliferation and metastasis by down-regulating KLF4 both in vitro and in vivo." (PMID 27302923, 2016).
tumor (continued). "Notably, the expression of both KLF4 and AR was low in tumor tissue samples with low miR-1 expression." (PMID 27991915, 2016). "Similarly, stemness transcription factors, Nanog, Oct4, KLF4, Lin28, and Sox2 were enriched in tumor spheres." (PMID 27259269, 2016). "Likewise, KLF-4 induces p21 expression in a context-specific manner, such that inactivation of p21 converts KLF-4 from a tumor suppressor to a tumor promoter." (PMID 27626309, 2016). "Importantly, these artificially generated KLF4α/KLF4(FL) ratios are in the range of the ratios observed in tumor patients." (PMID 27323810, 2016). "However, there is growing evidence indicating that KLF4 actually inhibits tumor formation and metastasis in many types of cancer." (PMID 27148537, 2016). "Consistent with its expression in these tumors, KLF4 plays an active role as a tumor suppressor." (PMID 27105535, 2016). "In addition, hTERT is an identical target of Wnt/β-catenin signaling in cancer cells, while KLF4 directly interacts with Wnt/β-catenin signaling to suppress Wnt signaling and inhibit tumor growth." (PMID 27153563, 2016). "A potential explanation for this discrepancy may be that the regulation of hTERT by KLF4 exhibits tissue-specific characteristics, which may be from the different roles that KLF4 plays depending on the tumor type." (PMID 27153563, 2016). "Finally the third network shows the link among the tumor suppressive microRNA, miR-145, KLF4, p65, and the Heat Shock 70 kDa Protein (HspA1A)." (PMID 26880947, 2016). "We found lower levels of KLF4 in tumor tissues compared with normal adjacent tissues." (PMID 27153563, 2016). "Reported tumor-suppressive effects of forced KLF4 expression include the induction of the epithelial cell-adhesion molecule E-Cadherin and the cell cycle inhibitors p21Cip1 and p27Kip1 via direct binding of KLF4 to the respective promoter elements." (PMID 27323810, 2016). "Thus, KLF4 plays an important role in tumor development and progression, while the molecular basis of this process requires further elucidation." (PMID 27153563, 2016). "Because KLF4 functions as an antiproliferative factor in differentiated epithelia, it seems that KLF4 might act as a tumor suppressor." (PMID 26823670, 2016). "KLF4 has been confirmed as both tumor suppressor and tumor promoter in different types of cancer." (PMID 27302923, 2016). "KLF4 is a zinc finger transcriptional factor involved in regulating numerous physiological processes, including proliferation, apoptosis, differentiation and tumor formation." (PMID 27153563, 2016). "In addition, we found that the tumor suppressor candidate genes kruppel-like factor 4 (klf4) and myo18b were up-regulated in this cluster." (PMID 27254593, 2016). "The overexpression of OCT4, SOX2, and KLF4 can reprogram or dedifferentiate somatic cells into induced pluripotent stem cells, which resemble the de-differentiation process that cancer cells undergo during tumor formation." (PMID 26582602, 2015). "In many human cancers KLF4 is regarded as a tumor suppressor." (PMID 25944097, 2015). "We next examined the impact of endogenous KLF4-miR-206 signaling on tumor initiation." (PMID 26053033, 2015). "In TNBC cells, both KLF4 and miR-206 were critical for cell survival and in vivo tumor initiation." (PMID 26053033, 2015). "In cultured and nude mouse xenografts of OSCC cells, KLF4 over-expression inhibited cell proliferation and colony formation, promoted cell cycle arrest in vitro, and inhibited tumor growth, suppressed angiogenesis, induced apoptosis, and transcriptionally activated p21 in vivo." (PMID 26517087, 2015). "It has been well-established that KLF4 acts as a tumor suppressor in many types of cancers." (PMID 25944097, 2015).
tumor (continued). "In addition, combined suppression of KLF4/5 in cultured tumor cells additively inhibited anchorage-independent growth, resistance to anoikis and tumor formation in immunocompromised mice." (PMID 25789974, 2015). "In B cells, KLF4 has been reported to halt cell cycle progression and act as a tumor suppressor." (PMID 26431332, 2015). "Mechanistically, MMP-9, a key mediator of tumor cell invasion, might involve in the KLF4-mediated migration and invasion." (PMID 26517087, 2015). "In contrast, down-regulation of KLF4 was detected in tumor tissues." (PMID 26087183, 2015). "To confirm this data in tumor cells, we performed ChIP assay with the primer of KLF4 promoter." (PMID 25879941, 2015). "Thus, KLF4 exerted its antitumor activity by inhibiting tumor cell proliferation and angiogenesis and by inducing apoptosis in vivo." (PMID 26517087, 2015). "Because KLF4 is a tumor suppressor clearly involved in the initiation and (or) progression of HCC, it would be reasonable that important regulatory checks on its expression may exist at multiple levels." (PMID 26087183, 2015). "Conversely, methylation of Rp and loss of either KLF4 and/or BLIMP1 expression might be one of the mechanisms by which EBV achieves latency in these tumor cells." (PMID 26431332, 2015). "Depletion of KLF4 reduced the tumor initiation rate of MDA-MB-231 cells in athymic nude mice." (PMID 26053033, 2015). "The tumor suppressor Klf4 activates p21 transcription and inhibits cell proliferation." (PMID 25257395, 2014). "KLF4 has yielded ambiguous results regarding its oncogenic yet tumor suppressing role." (PMID 24429391, 2014). "The tumor-suppressive role of KLF4 and its involvement in regulating apoptosis, proliferation, and differentiation in B-cell malignancies suggest that KLF4 may play a critical role in leukemogenesis." (PMID 25037230, 2014). "The KLF4 gene has been shown to be inactivated in cervical carcinogenesis as a tumor suppressor." (PMID 24551169, 2014). "Thus, we conclude that miR-7 acts as an oncomiR in the epithelial cellular context, where through the negative regulation of KLF4-dependent signaling pathways, miR-7 promotes cellular transformation and tumor growth." (PMID 25181544, 2014). "Our results support the hypothesis that KLF4 promoter methylation inactivates the gene’s function as a tumor suppressor in cervical carcinogenesis." (PMID 24551169, 2014). "The expression of KLF4 was significantly correlated with tumor differentiation (p = 0.001)." (PMID 24897024, 2014). "KLF4 is a TF that can act as a tumor suppressor or as an oncogene." (PMID 25181544, 2014). "Thus, depending on the genetic and epigenetic context of the cell type, KLF4 can act as a tumor suppressor or as an oncogene." (PMID 25181544, 2014). "In contrast to Aldh1a2, Klf4 is expressed in epithelial components of the primary tumor." (PMID 25242334, 2014). "In this study, we characterized the epigenetic regulation of the pluripotency-associated genes NANOG, OCT4, c-MYC, KLF4, and SOX2 in a variety of cancer cell lines and in primary tumor samples, and investigated the re-activation of pluripotency regulatory circuits in cancer progression." (PMID 24023739, 2013). "Altered expression of Klf4, Sox2, Oct4, Nanog and c-Myc genes indicates the abundance of cancer stem-like cells (CSLCs) in primary tumors that may be key resources for tumor progression and the poor prognosis of HCC." (PMID 23599755, 2013). "Patients with weakly or negatively stained KLF4 had larger tumor size and higher tumor stage." (PMID 23861801, 2013).
tumor (continued). "In addition, expression of epithelial marker E-cadherin is retained at the cell membrane while expression of mesenchymal markers N-cadherin and fibronectin are decreased after Klf4 induction in tumor sections." (PMID 23451207, 2013). "KLF4 downregulation was significantly correlated with tumor stage and tumor diameter." (PMID 23861801, 2013). "Notably, positive expression of Klf4 mRNA was also correlated with tumor relapse and a poor prognosis in patients with HCC." (PMID 23599755, 2013). "In summary, our data showed that KLF4 functioned as a tumor suppressor in ccRCC pathogenesis." (PMID 23861801, 2013). "However, our experimental results also reveal that Klf4 not only prevents lung and liver metastasis but also provides a survival advantage to cells, thus leading to increased primary tumor growth." (PMID 23451207, 2013). "We also found that KLF4 could be a novel tumor suppressor in the development and/or progression of ccRCC." (PMID 23861801, 2013). "Several pieces of data presented in this manuscript strongly support the hypothesis that KLF4 acts as a tumor suppressor in HCC." (PMID 22937066, 2012). "Whether the down-regulation of KLF4 by hypoxia has a direct role in the promotion of tumor angiogenesis needs further investigation." (PMID 23185562, 2012). "Collectively, our data support a tumor suppressor function for KLF4 in HCC." (PMID 22937066, 2012). "Thus, our data suggest that ectopic Klf4 expression inhibits tumor growth and lung colonization by HCC cells in vivo." (PMID 22937066, 2012). "Before the study reported herein, it was unknown whether KLF4 displayed tumor-suppressive or oncogenic properties in HCC." (PMID 22937066, 2012). "Ectopic Klf4 expression impaired subcutaneous tumor growth and lung colonization in vivo." (PMID 22937066, 2012). "KLF4 has been suggested to act as an oncogene or tumor suppressor in different tumor types." (PMID 22937066, 2012). "Importantly, multiple lines of evidence showed that KLF4 can function as an oncogene or a tumor suppressor depending on the type of cancer involved." (PMID 22937066, 2012). "Therefore, the inhibition of Wnt/β-catenin signaling by Klf4 plays an important role in the regulation of normal intestinal homeostasis and tumor repression." (PMID 21687630, 2011). "Therefore, we used three factors (Oct3/4, Klf4, and Sox2), eliminating c-Myc, with a special emphasis on escape from tumor development." (PMID 21789202, 2011). "One possible explanation for the differential expression of Sox1, Oct4 and Klf4 in low and high grade tumors, is that these tumor types may constitute distinct disease entities." (PMID 21483788, 2011). "Mouse models have further highlighted the tumour suppressor versus oncogenic function of Klf4." (PMID 20514221, 2009). "Moreover, KLF4 overexpression led to a suppression of tumour cell growth both in vitro and in vivo, as shown for AP-2α." (PMID 19672266, 2009). "Inversely, level of KLF4 transcript is significantly decreased in intestine during tumor formation in Min mice, a model of intestinal tumorogenesis, suggesting that KLF4 may play a role in gut development and/or tumor burden." (PMID 20119532, 2009). "Enforced expression of KLF4 results in cell proliferation and tumor growth inhibition." (PMID 20119532, 2009). "Therefore, targeting KLF4 to favorably alter the phenotypic ratio of TAMs, characterized by a reduction in M2 macrophages and an increase in M1 macrophages, represents a promising therapeutic strategy to promote anti‐tumor immunity." (PMID 41532367, 2026).